FLT3 (fms related receptor tyrosine kinase 3)
Diseases named in the same sentence as FLT3 in open-access papers (continued):
Sharing a sentence is not in itself a finding about the gene and the disease.
leukemia (continued). "This study investigates the anti-leukemia activities of active G. pentaphyllum leaf extracts and their components, focusing on the inhibition of FLT3 and WT1 activity." (PMID 40361130, 2025). "It uses two activating CARs (CD33 and FLT3) as an OR-gate to destroy leukemia cells with either antigen, countering tumor diversity." (PMID 41487532, 2025). "While the fms-like tyrosine kinase-3 (Flt3) has been extensively studied in the context of blood cell development and leukemia pathogenesis, its role in the brain remains poorly understood." (PMID 40076904, 2025). "In contrast, FLT3-ITD emerged as a strong independent adverse prognostic factor in intermediate- and high-risk groups, directly contributing to leukemia cell resistance to initial induction chemotherapy." (PMID 41294667, 2025). "For instance, the internal tandem duplication (ITD) mutation in the Fms-like tyrosine kinase 3 gene (FLT3/ITD) induces metabolic alteration and makes leukemia cells highly dependent on glycolysis." (PMID 40346054, 2025). "The evolving treatment landscape, aided by the widespread availability of next-generation sequencing, has brought FLT3 alterations into sharper focus across multiple leukemias." (PMID 41228209, 2025). "Due to the co-occurrence of FLT3 mutations in DEK::NUP214 patients, we examined the potential synergy of eltanexor and gilteritinib, an FTL3 inhibitor, in five leukemia cell lines." (PMID 40148556, 2025). "To investigate the role of HDACis in leukemia maintenance and drug resistance, we generated the FLT3i-resistant AML cells MV-4-11/quizartinib harboring FLT3-ITD and F691L mutations, exhibiting a resistance factor (RF) of 5717 for quizartinib." (PMID 39955584, 2025). "By targeting FLT3 dysregulation, researchers and clinicians aim to curb the proliferation of leukemia cells and improve clinical outcomes in this subset of patients." (PMID 40547482, 2025). "In this study, we investigated the regulation of FLT3/ITD mutation on SREBP and the therapeutic vulnerabilities of fatty acid metabolism in FLT3/ITD leukemia." (PMID 40263296, 2025). "In MOLM13 leukemia cells, FLT3 inhibitor 3i-1247 was the most potent compound overall, and possessed superb anti-proliferative activity compared to dual FLT3/TAF1 compounds 3i-1246 and 3i-1248." (PMID 40153395, 2025). "The in vivo anti-leukemia efficacy was tested in xenografted mice models derived from FLT3-ITD cell lines and primary AML patients." (PMID 39955584, 2025). "Studies identified PDP1 as a modulator of drug resistance in the Fms-like tyrosine kinase 3- internal tandem duplications (FLT3-ITDs) positive leukemia." (PMID 40491447, 2025). "Taken together, these findings indicated a mechanistic link between modulation of SREBP mediated lipid metabolism and FLT3-targeted therapy of FLT3/ITD leukemia." (PMID 40263296, 2025). "Although much remains to be overcome, research and innovation continue to evolve these therapies, highlighting the promise of durable remissions and improved survival of patients with FLT3-driven leukemia." (PMID 40547482, 2025). "We also performed ChIP-seq for SETD1B and SETD1A using HA-tagged SETD1B or SETD1A expressing MOLM-13 human MLL-r/FLT3-ITD leukemia cells." (PMID 40341256, 2025). "FLT3 mutations (D835 and ITD) are detected in patients with leukemia with mixed-lineage leukemia-rearrangement (MLL-r), caused by a translocation of H3K4 methyltransferase (H3K4HMT) MLL1 (also known as KMT2A)." (PMID 40341256, 2025). "Single and dual TAF1/FLT3 inhibitors were tested for activity against MOLM13 leukemia cells based on reduction in Cell-titer Glo activity, which corresponds to the number of viable cells, and CellTox Green, which corresponds to the number of dead cells." (PMID 40153395, 2025). "This upregulation is associated with ERK reactivation, and concurrent FLT3 and AXL inhibition diminishes adaptive ERK reactivation and sensitizes leukemia cells to FLT3 TKI treatment." (PMID 39395205, 2025).
leukemia (continued). "Specifically, JNK, activated by ROS and endoplasmic reticulum stress (e.g., via IRE1α), is required for survival of FLT3-ITD leukemia cells, and its pharmacologic inhibition using SP600125 induces apoptosis even in TKI-resistant FLT3-ITD-TKD blasts." (PMID 41003134, 2025). "In vitro assays found that FLT3-20D9h3-DUBA completely eliminated leukemia progenitor cells and prevents engraftment of patients-derived xenograft cells (PDX) in NSG mice." (PMID 40429716, 2025). "FLT3-ITD cause constitutive RAS signaling pathway activation and alter the epigenetic landscape and gene expression in leukemia." (PMID 40341256, 2025). "Previous work in our lab showed that FLT3 inhibition induces an adaptive response that is discernible within 16–24 h of treatment of leukemia cells, resulting in reactivation of ERK signaling just hours after starting treatment." (PMID 39395205, 2025). "The functional importance of lipid metabolism in FLT3/ITD leukemia has remained to be further investigated." (PMID 40263296, 2025). "One of our important findings in this study is that quizartinib caused rapid degradation of SREBP and specifically downregulated the levels of major species of phospholipids in FLT3/ITD leukemia cell lines." (PMID 40263296, 2025). "This study aims to investigate the anti-leukemia activities of G. pentaphyllum ethyl acetate extract on EoL-1 cells expressing human wild-type FLT3 (FLT3-WT) and MV4-11 cells harboring internal tandem duplication mutants of FLT3 (FLT3-ITD)." (PMID 40361130, 2025). "Drug-tolerant leukemia cells that survive FLT3 inhibitor treatment, characterized by upregulation of inflammatory pathways." (PMID 40443513, 2025). "A subset of NPM1c NK-AML shows additional mutations in 2 genes: FLT3 (FLT3-ITD) and DNMT3 A. These leukemias, also referred to as NK triple mutated AML (NKt-AML), are particularly difficult to eradicate with current treatment options." (PMID 40229904, 2025). "Despite these findings, the anti-leukemia mechanisms of G. pentaphyllum in relation to the leukemia cell proliferation markers FLT3 and WT1 remain unexplored." (PMID 40361130, 2025). "We then determined the half-maximal inhibitory concentration of the specific and potent FLT3 inhibitor, gilteritinib, in human FLT3-ITD leukemia cell lines after 24 h of treatment." (PMID 40092706, 2025). "In FLT3-ITD-positive leukemia, these metabolic changes led to resistance, marked by mitochondrial dysfunction and increased glycolysis, which supported tumor growth." (PMID 41479777, 2025). "After 8 weeks of treatment, 21 patients achieved CR (80.8%, 95% CI, 62.1% - 91.5%); including 87% (13/15) patients with FLT3-WT leukemia." (PMID 40083897, 2025). "Quizartinib inhibits cell proliferation and induces apoptosis in leukemia cell lines that are dependent on Flt3." (PMID 37945814, 2024). "More importantly, the overexpression of FLT3 significantly restored the cell expansion in the RBM5 sgRNA-treated leukemia cells, similar to the extent of both RBM5 and HOXA9 overexpression." (PMID 38216972, 2024). "AML-derived mutations of FMS-like tyrosine kinase 3 (FLT3) upregulated SUCLG1 to induce POLRMT hyposuccinylation, resulting in enhanced mitobiogenesis and leukemia progression." (PMID 38649537, 2024). "First, we used BALB/c mice to construct FLT3-ITD-F691L leukemia model to evaluate the efficacy of ningetinib in vivo." (PMID 38978049, 2024). "HSPs stabilize oncoproteins, such as fusion proteins resulting from chromosomal translocations in leukemia, and key tumor-promoting kinases, such as FLT3, RAF, and AKT." (PMID 39300221, 2024). "Fluvastatin has the potential to induce cytotoxic effects in mutant FLT3 leukemia cell lines through the disruption of signal transduction pathways, thus reducing tumor burdenin vivo." (PMID 38915288, 2024).
leukemia (continued). "This dual-targeting Co-Assembled formulation exhibits cytotoxic effects on AML cells (AML cell lines and primary blasts), reduced leukemia burden and prolonged survival in FLT3-ITD AML mouse models." (PMID 39007347, 2024). "In mouse models, the combination of NUP98 fusion and FLT3-ITD alterations leads to a more aggressive form of leukemia with a shorter latency period." (PMID 39068406, 2024). "Tunicamycin demonstrated significant efficacy in reducing the viability of leukemia cell lines expressing FLT3-ITD and displayed synergistic effects with FLT3-ITD kinase inhibitors." (PMID 38915288, 2024). "Anti–TIM-3 treatment also reduced the leukemia burden in FLT3-ITD MLL-PTD–driven AML, as evidenced by decreased AML cell frequency in the BM at day 23 after allo-HCT." (PMID 38916965, 2024). "In vivo activity of MA49 against FLT3-ITD-positive leukemia cells is verified in a Danio rerio model." (PMID 39300221, 2024). "Lestaurtinib is a multi-target FLT3 (Fms-like Tyrosine Kinase-3) inhibitor with confirmed efficacy in inhibiting phosphorylation and inducing cell death in primary leukemia samples and in vivo mouse model studies." (PMID 38474445, 2024). "In contrast, other genomic abnormalities, including mutations in FLT3, NRAS, and RUNX1, tend to be acquired later during leukemia development." (PMID 39590121, 2024). "The fms-related tyrosine kinase 3 gene (FLT3) encodes a receptor in the FMS family, and was originally implicated in leukemia biology in the early 1990s with northern blot analysis identifying high levels of expression in blasts." (PMID 38571944, 2024). "The mutated FLT3 kinase activates the PI3K/AKT, JAK/STAT5, and MEK/ERK pathways and promotes leukemia progression." (PMID 38927401, 2024). "Enasidenib therapy in FLT3-ITD + /IDH2 R140Q double mutated mice model decreased the 2-HG serum levels and induced demethylation of the hypermethylated promoters in leukemia-derived cells." (PMID 38696033, 2024). "While activating mutations in FLT3 are relatively rare in infants suffering from ALL, the overexpression of wild-type FLT3, causing autoactivation, is a notable characteristic and high-risk factor in KMT2A-r leukemias." (PMID 38612531, 2024). "It has been demonstrated that cabozantinib induces apoptosis in FLT3-ITD+ leukemia cells in a dose-dependent manner." (PMID 39367387, 2024). "ULK1 inhibitors effectively induce mitochondria-mediated, caspase-dependent apoptosis in FLT3-ITD-mutated leukemia cell lines and primary leukemia cells." (PMID 38307903, 2024). "The SMGs identified in our mouse models included well-described melanoma and leukemia oncogenes and tumour suppressors (Muc4, Pten, Grin2a, Dnmt3a, Npm1 and Flt3) reinforcing the WES validation and the subsequent filtering of SMGs." (PMID 39223638, 2024). "focused on leukemia stem cells' genetic composition, while our study focuses on FLT3‐ITD mutant AML cell lines derived from human samples." (PMID 38334474, 2024). "In the mouse models with FLT3-ITD and FLT3-ITD-F691L mutation, ningetinib showed superior anti-leukemia activity to existing clinical drugs gilteritinib and quizartinib, significantly prolongating the survival of mice." (PMID 38978049, 2024). "FLT3 also has limited expression in normal tissue, primarily found in early hematopoietic progenitors and leukemia blasts." (PMID 39697225, 2024). "For example, mutations in FLT3, a common driver mutation in AML, are frequently observed in trisomy 8 AML and have been shown to cooperate with trisomy 8 to induce leukemia in mouse models." (PMID 39459611, 2024). "Combined use of AC220 and olaparib eliminated FLT3-positive quiescent and proliferating leukemia stem cells, as well as reducing leukemia initiating cells." (PMID 39175540, 2024). "Sorafenib is a multi-kinase inhibitor which was initially studied in leukemia cell lines as a potent inhibitor of FLT3 enzymatic and signaling activity." (PMID 38571944, 2024).
leukemia (continued). "Because Flt3-signaling is potently anti-apoptotic in leukemia cells, we focused our study on apoptosis." (PMID 37945814, 2024). "The increased SOCS1 level in the bone marrow of AML patients was closely associated with advanced age, mutations in FLT3-ITD, NPM1, and DNMT3A, and SOCS1 overexpression in zebrafish mimic leukemia phenotype." (PMID 38161382, 2023). "In line with the well-established role of metabolism in drug sensitivity in AML and considering the central metabolic functions of PDP1, we aimed to investigate the relevance of PDP1 as a modulator of leukemia response to FLT3 inhibitors." (PMID 37935978, 2023). "In order to show that PDP1 dependency is indeed due to its metabolic function, we made use of another model, where we engineered an FLT3-ITD-expressing leukemia cell line that proliferates independently of mitochondrial energy production (Rho Zero cells)." (PMID 37935978, 2023). "Leukemia cells often display various mutations, for instance, the FMS-like tyrosine kinase 3 (FLT3)-internal tandem duplication (FLT3/ITD) mutation is observed in 30% AML." (PMID 37887047, 2023). "Arsenic trioxide has relative selective activity on FLT3-ITD cells (MOLM14, MV-4-11, and HB11;19) compared with non-FLT3-ITD leukemia cells (HL-60, SEM-K2, THP-1, U-937, and K-562)." (PMID 37500645, 2023). "This is of particular importance for difficult to treat leukemias such as FLT3 internal tandem duplication (ITD) positive AML." (PMID 36739348, 2023). "Our use of integrative genetic tools revealed the HOXA9-binding and cis-regulatory regulation mechanism of FLT3 in MLL-r leukemia models." (PMID 38016946, 2023). "We found that CG-806 has superior anti-leukemia effects against both FLT3 WT and mutant AML, especially in AML harboring FLT3 and TKD point mutations, which is a potential mechanism of secondary resistance to FLT3i." (PMID 36865133, 2023). "In the same line, an RNA oligonucleotide that inhibits CXCL12, showed synergistic activity in combinatorial treatment with midostaurin against FLT3-ITD-dependent leukemia cells." (PMID 37849810, 2023). "Results indicated that CG-806 blocked cells in G1 phase in FLT3-ITD-mutated MOLM14 and MV4–11 leukemia cell lines after 24 h of treatment as determined by BrdU incorporation assay." (PMID 36865133, 2023). "In terms of cellular pathways, these genes are mainly associated with mutations in the interleukin pathway and in the FLT3 and KIT genes (which are also mainly associated with leukaemia)." (PMID 38127054, 2023). "In the initial experiments, we showed that PDP1 expression is enhanced in FLT3-ITD-dependent leukemia cells, and thus it seemed at first sight surprising that FLT3 inhibition enhanced PDP1 expression in these cells even further." (PMID 37935978, 2023). "A recent clinical trial with the FLT3 inhibitor lestaurtinib revealed that patients whose leukemia blasts exhibited sensitivity to FLT3 inhibition ex vivo experienced benefits from the addition of the FLT3 inhibitor to chemotherapy." (PMID 37686014, 2023). "We report on a transgenic murine model of FLT3-ITD induced disease, where Cre recombinase expression alone, and in the absence of a conditional allele, gives rise to an aggressive leukemia phenotype." (PMID 36739348, 2023). "The VTP-50469 targets the expression of FLT3 by inhibiting leukemia transcription factor MEIS1 and promotes the loss of phosphorylated FLT3 mediated by FLT3 inhibitors, thus producing a synergistic antileukemia impact on NPM1mut or MLL-r leukemia." (PMID 37049787, 2023). "Similarly, we deduced that the degradation of FLT3 mutation oncoprotein involved with bortezomib may also eradicate FLT3-mutated leukemia cells, and then it will achieve better therapeutic effects when combined with other drugs, such as FLT3 inhibitor or chemotherapy agents." (PMID 37664023, 2023).
leukemia (continued). "We isolated primary leukemia cells from Npm1c, Flt3-ITD Cas9 mice, cultured them and used cellular indexing of transcriptomes and epitopes sequencing (CITE-seq) to interrogate their differentiation status." (PMID 37580596, 2023). "A novel therapeutic strategy has been developed for FLT3‐ITD+ leukemia by promoting FLT3 depalmitoylation." (PMID 37143582, 2023). "NUP98::rearranged AML are now recognized as a high-risk subtype of leukemia, and NUP98-NSD1 was found in 15% of FLT3/ITD and 7% of cytogenetically normal (CN)-AML." (PMID 36629738, 2023). "FLT3-ITD mutation enhances autophagy in AML cells via ATF4, prolongs the lifespan of leukemia cells, and induces tolerance to FLT3 inhibitors." (PMID 37189112, 2023). "Above result demonstrated that although the anti-FLT3-ITD leukemia cells effect in vivo was weaker than AC220, GNF-7 showed the equal effect as gilteritinib." (PMID 38037057, 2023). "This was especially pronounced for cBAF and COMPASS members, revealing Npm1c and Flt3-ITD leukemia to be highly dependent on the epigenetic activities regulated by these complexes." (PMID 37580596, 2023). "Previous work by us and others highlighted the importance of the RAS pathway in the oncogenic signaling and transformation of FLT3-ITD-positive leukemia and in this study, we extend this to its role in maintaining PDP1-driven OXPHOS." (PMID 37935978, 2023). "Taken together, CG-806 demonstrates superior anti-leukemia activity in vitro and in vivo compared to other FLT3i by suppression of FLT3/BTK/AURK simultaneously." (PMID 36865133, 2023). "NRAS/KRAS mutations frequently emerge at relapse in patients treated with clinical FLT3 inhibitors, and Ras oncoprotein expression rescues FLT3-mutant leukemia cell lines from drug-induced apoptosis." (PMID 37681415, 2023). "Taken together, we show that GNF-7 is a very potent FLT3 inhibitor that exerts strong anti-leukemia effects against AML cells harboring FLT3-ITD and FLT3-ITD/F691L both in vitro and in vivo, which is recognized as the difficult mutation to overcome clinically." (PMID 38037057, 2023). "As a result, compound 5 has selective cytotoxicity on the FLT3-expressing leukemia cells over normal cells." (PMID 37438819, 2023). "Targeting FLT3 and Bcl-2 and/or Mcl-1 simultaneously resulted in a synergistic pro-apoptotic effect in FLT3mutant leukemia cells." (PMID 36865133, 2023). "Of note, GNF-7 exerts the same therapeutic effect as gilteritinib in a FLT3-ITD mouse xenograft model and significantly prolongs the survival of FLT3-ITD/F691L leukemia mice." (PMID 38037057, 2023). "GNF-7 exerted very potent inhibitory effect on the proliferation of FLT3-ITD AML leukemia cells (AML #3, AML #4, AML #5) compared with normal mononuclear cells or none FLT3-ITD mutation AML cells." (PMID 38037057, 2023). "We tested the inhibition of MV-4–11 leukemia cells by TKIs sorafenib, sunitinib, and quizartinib, which have been clinically proven to be effective in FLT3-ITD-posiotive AML." (PMID 37454155, 2023). "Compared with gilteritinib, the same concentration of GNF-7 had a stronger inhibitory effect on leukemia cell proliferation in three FLT3-ITD AML patients." (PMID 38037057, 2023). "The preliminary results show that Amg553’s CAR-T cells target FLT3-expressing leukemia cells but spare normal hematopoietic stem cells, reducing therapeutic side effects." (PMID 37330575, 2023). "The CLSG/GCEL panel believes that at present, most leukemia centers in Canada perform upfront PCR-fragment analysis for FLT3-ITD detection (to take advantage of the fast turnaround time) and perform NGS to identify other clinically relevant mutations." (PMID 38132393, 2023). "Further studies confirmed the effectiveness of anti-FLT3 CAR-R2 T cells in the eradication of leukemia, and the administration of rituximab resulted in the depletion of CAR-T cells, thus limiting hematotoxicity and enabling BM recovery." (PMID 37296906, 2023).